SNORD3P1 (small nucleolar RNA, C/D box 3 pseudogene 1)
Synonyms: U3; RNU3P1
Gene: Small nucleolar RNA gene on chromosome 15 (58,760,466 to 58,760,681, reverse strand). Ensembl gene ENSG00000200318.
Homologues: Orthologues: chimpanzee U3 (99% identical), macaque U3 (92% identical), macaque U3 (29% identical). Paralogues in human: U3 (88% identical), SNORD3E (86% identical), U3 (84% identical), U3 (83% identical), U3 (82% identical), SNORD3G (82% identical), SNORD3H (82% identical), U3 (81% identical), SNORD3D (81% identical), U3 (80% identical), U3 (79% identical), U3 (78% identical), and 11 more.